INS (insulin)
Diseases named in the same sentence as INS in open-access papers (continued):
Sharing a sentence is not in itself a finding about the gene and the disease.
type 2 diabetes (continued). "Several treatments for type 2 diabetes (e.g. sulfonylureas, meglitinides, glucagon-like peptide-1 [GLP-1] receptor agonists and dipeptidyl peptidase-4 [DPP-4] inhibitors) directly stimulate beta cells to increase insulin release." (PMID 24585202, 2014). "Fibres such as pectin and guar reduce gastric emptying but pectin tends to lower insulin without an effect on glucose levels in normal subjects while guar lowers both in people with diet controlled type 2 diabetes." (PMID 25343850, 2014). "In addition to its key role in the maintenance of glucose homeostasis, insulin and its receptor (INSR) are involved in the development of a number of metabolic conditions, including obesity and type 2 diabetes." (PMID 24434591, 2014). "Under the conditions of severe burn injury and sepsis, impaired insulin function could affect liver GCL expression, as has been demonstrated in type II diabetes condition." (PMID 27574630, 2013). "The apparent protective role of magnesium on IR and type 2 diabetes has not been fully explained but is likely due to enhanced insulin sensitivity through multiple mechanisms." (PMID 23472169, 2013). "Several studies focused on the use of exenatide BID and insulin (basal with or without prandial) combination therapy in patients with obesity and type 2 diabetes 42,47–49." (PMID 23061470, 2013). "It is ironic indeed, that originally fructose was proposed as the ideal sweetener for persons with Type 2 Diabetes because it does not raise blood sugar and is unable to stimulate insulin secretion." (PMID 23896654, 2013). "Although the effects of dietary fiber on insulin sensitivity have not been studied in type 2 diabetic patients, dietary fiber enhances insulin sensitivity in hepatic and peripheral tissues in insulin-resistant obese subjects." (PMID 24330576, 2013). "The translated questionnaire was piloted on 303 insulin naïve (never taken insulin) Type 2 diabetes patients recruited from 10 government-funded primary care clinics across Hong Kong." (PMID 24236071, 2013). "ORIGIN on the other hand provided evidence that insulin initiated early in the course of type-2 diabetes does not generally increased of hypoglycaemia." (PMID 24053606, 2013). "Although none of the islet donors were diagnosed with type 2 diabetes, nearly all of the cadaver-derived human islets that we receive display insulin signaling pathway resistance as determined by decreased response to exogenous insulin or IGF-1." (PMID 23650507, 2013). "Paradoxically, circulating FGF-21 is increased in obese nondiabetic subjects and in newly diagnosed type 2 diabetes, where it correlates positively with adiposity and fasting insulin." (PMID 23533568, 2013). "Insulin therapy is a widespread therapeutic modality for advance type 2 diabetes when other medications have failed to maintain reasonable glycemic control." (PMID 23408938, 2013). "Type 2 diabetes results when the β-cells of the pancreas are no longer capable of producing sufficient insulin to meet the body’s demands." (PMID 23442068, 2013). "The regulation of the GLUT4 protein of insulin-target tissues is well established as occurring downstream of the insulin receptor and PI3K (phosphoinositide 3-kinase) signalling and is known to become dysfunctional in human obesity and Type 2 diabetes." (PMID 24024580, 2013). "Ten type 2 diabetic patients undergoing hemodialysis received daily 0.3 mg liraglutide, 50 mg vildagliptin, and 6.25 mg alogliptin switched from insulin therapy on both the day of hemodialysis and the non-hemodialysis day." (PMID 23445717, 2013). "Although the effect of SMBG already demonstrated in some meta-analysis, it is not recommended as regularly use in non-insulin treated type 2 diabetes." (PMID 23876067, 2013). "Several such formulations have been developed, but their clinical superiority over currently available rapid-acting insulin analogues in type 2 diabetes is questionable, and it has never been demonstrated so far." (PMID 24348585, 2013).
type 2 diabetes (continued). "Indeed, metformin, a common pharmacological treatment for type 2 diabetes, targets AMPK subsequently, increasing insulin sensitivity." (PMID 23829931, 2013). "Diabetic macular edema (DME) was present in 4.1% of type-2 diabetic patients not requiring insulin and 9.1% in those with insulin in the longitudinal Exeter Diabetic Retinopathy Screening Program in the UK." (PMID 23574917, 2013). "The identification of GLP-1 analogs that promote insulin secretion to treat type-2 diabetes without inducing pro-tumoral effects is therefore a timely challenging issue." (PMID 23641235, 2013). "Furthermore, in type 2 diabetes patients, PPAR-γ agonists reduce the serum levels of SAA in parallel with an improvement of glycemic status and insulin sensitivity." (PMID 23967285, 2013). "Thus, we found that only in subjects with type 2 diabetes, serum leptin levels depend on HOMA-IR calculated using insulin and glucose concentrations." (PMID 23853613, 2013). "People with type 2 diabetes who were not treated with insulin were identified from a US-based employer claims database (1998–2010)." (PMID 23121373, 2013). "We assessed the urinary C‐peptide creatinine ratios, from urine samples taken at home 2 h after the largest meal of the day, in 191 insulin‐treated subjects with Type 2 diabetes (diagnosis age ≥45 years, no insulin in the first year)." (PMID 23659458, 2013). "The objective of this study was to assess the relationship between hypoglycaemia and risk of accidents resulting in hospital visits among people with type 2 diabetes receiving antidiabetes drugs without insulin." (PMID 23121373, 2013). "Although many Asian type 2 diabetic patients have been considered to be not obese and have low capacity of insulin secretion, the proportion of obese patients with visceral fat accumulation has increased in recent years." (PMID 23773268, 2013). "Type 1 diabetes results from inadequate synthesis of insulin by β-cells of the pancreas, while type II diabetes is characterized primarily by insulin resistance (a condition in which peripheral cells do not respond normally to insulin) or β-cell dysfunction." (PMID 24455701, 2013). "This, in turn, is influenced by their genetic constitution which explains why some obese and insulin resistant individuals do not develop type 2 diabetes; their beta cells can compensate." (PMID 23542897, 2013). "There is a link between 25(OH)D levels and insulin responsiveness of tissues as well as between glucose levels and glycosylated hemoglobin in people without diabetes mellitus type 2." (PMID 23924693, 2013). "Down-regulated genes (left quadrants) involve cytokine-cytokine receptor interactions pathways (KEGG 04060), whereas genes that are early up-regulated (lower right quadrant) are involved in pathways such as Type II diabetes mellitus (KEGG 04930) and insulin signaling pathway (KEGG 04910)." (PMID 23742070, 2013). "The beneficial roles of insulin on skeletal health has been entertained by many authors, supported by the observations that lower BMD in type 1 diabetes and higher BMD in subjects with type 2 diabetes." (PMID 25258705, 2013). "Current evidence favours that insufficient glucose-stimulated insulin secretion is primarily responsible for type 2 diabetes; however, the site of the beta cell defect in type 2 diabetes is not known." (PMID 23766565, 2013). "Body weight, blood glucose and plasma insulin levels were monitored to demonstrate that this drug that had originally had been developed as a treatment for type 2 diabetes does not affect these parameters." (PMID 23601582, 2013). "This remarkable result indicates that NO may help to compensate the energy metabolism by improving leptin and insulin levels, and HOMA-IR, HOMA-β in type 2 diabetes." (PMID 23251156, 2012).
type 2 diabetes (continued). "This review examines the benefits and risks of adding exenatide twice daily, a glucagon-like peptide 1 (GLP-1) receptor agonist, in patients with type 2 diabetes who are currently treated with basal insulin, but have failed to reach their glycaemic goals." (PMID 23061886, 2012). "A significant reduction in insulin sensitivity was observed following two days of bed rest in participants with type 2 diabetes, but not in healthy adults." (PMID 22754695, 2012). "The spontaneously diabetic Torii (SDT) rat is a new model for nonobese type 2 diabetes that spontaneously develops hyperglycemia and glucose intolerance resulting from decreased insulin secretion accompanying β-cell degeneration." (PMID 23056035, 2012). "Stevioside was able to lower blood glucose in type 2 diabetic subjects and in a non-obese animal model of type 2 diabetes i.e. the Goto Kakizaki rat by both increasing insulin release and suppressing glucagon levels." (PMID 22479612, 2012). "Oxidative stress has therefore previously been proposed to enhance IR and type 2 diabetes, but to date antioxidant interventions in insulin resistant or diabetic patients and animal models have not confirmed its causal role for IR." (PMID 23028961, 2012). "In this regard, we also showed that GABA levels were decreased in STZ-diabetic synaptosomes compared to control synaptosomes and that insulin could modulate rat brain synaptosomal GABA and/or glutamate transport under oxidation and/or type 2 diabetes." (PMID 22500228, 2012). "Metformin has been widely used for treating type 2 diabetes without the stimulation of insulin production." (PMID 23056035, 2012). "In contrast, in type 2 diabetes with high frequency of concurrent obesity, insulin insensitivity rather than the degree of glucose intolerance is predictive of the occurrence of hepatic steatosis." (PMID 23039762, 2012). "Obviously, we cannot extrapolate the continuous relationship between 1-hour plasma glucose levels and alterations in insulin action and secretion to the general population, but the strong similarities existing between GDM and IGT/type 2 diabetes are worth being considered." (PMID 22567007, 2012). "This review assesses the benefits and risks of adding exenatide twice daily, a glucagon-like peptide 1 receptor agonist, in patients with type 2 diabetes who are currently treated with basal insulin, but have failed to reach their glycaemic goals." (PMID 23061886, 2012). "The role of mitochondria in obesity and type 2 diabetes has been confirmed by studies examining insulin resistant but otherwise, healthy individuals, with non-insulin-resistant subjects." (PMID 22203837, 2012). "Cross-sectional analysis was performed in 2086 well-controlled (HbA1c ≤58 mmol/mol, systolic blood pressure ≤145 mmHg, total cholesterol ≤5.2 mmol/l and not using insulin) type 2 diabetes patients in general practice." (PMID 23039172, 2012). "There is now evidence that a single bout of endurance (aerobic) or resistance exercise reduces 24 h post-exercise subcutaneous glucose profiles to the same extent in insulin-resistant humans with or without type 2 diabetes." (PMID 22391950, 2012). "Additionally, we showed that insulin prevented the decrease in GABA and glutamate uptake and their increased extrasynaptosomal levels in rat synaptosomes after oxidative stress and/or type 2 diabetes." (PMID 22500228, 2012). "The mid-stage study of INCB013739 demonstrated that treatment of type 2 diabetes mellitus patients with INCB013739 for 28 days significantly improved hepatic and peripheral insulin sensitivity and reduced fasting plasma glucose, plasma low density lipoprotein and total cholesterol levels." (PMID 23040895, 2012). "Recently, insulin and insulin-like growth factors (IGFs) have been suggested as important modifiers for the pathogenesis of neurodegenerative diseases, providing a link between obesity, type 2 diabetes (T2D), and cognitive impairment or even the pathogenesis of Alzheimer's disease." (PMID 22654904, 2012).
type 2 diabetes (continued). "Although obesity is a major risk factor for the development of type 2 diabetes, not all obese individuals become insulin resistant or develop type 2 diabetes." (PMID 22992414, 2012). "Along this line, a few previous studies in Europeans have shown that some genetic variants acting on insulin secretion (e.g., TCF7L2) have a greater impact on type 2 diabetes in non-obese subjects than in obese subjects." (PMID 23173044, 2012). "Our results are not consistent with the Hongkong study of type 2 diabetes which was based on 973 new insulin users and 971 matched non-users of insulin." (PMID 22719946, 2012). "In diabetic patients, the pancreas does not secrete insulin (type 1 diabetes) or problems in both insulin secretion and action (type 2 diabetes) occur, and as a consequence, glucose concentrations in blood often exceed the normal range (70–180 mg/dL)." (PMID 23202020, 2012). "The most reliable way to identify type 2 diabetes in our sample was to remove cases with a filled prescription for insulin, in the absence of repeated oral hypoglycemic prescriptions." (PMID 22920280, 2012). "These clinical studies clearly demonstrate that although not all Type 2 diabetes patients benefit from Imatinib therapy, there is a substantial proportion that responds, and some cases so dramatically that they become insulin-independent." (PMID 21935477, 2011). "The diagnosis was later corrected to type 2 diabetes by his consulting physician when it was determined that patient had never experienced ketoacidosis even after months of insulin omission." (PMID 22164267, 2011). "Insulin sensitivity is also reduced and negatively correlated to adipose cell size in non-obese subjects with heredity for Type 2 diabetes." (PMID 21532749, 2011). "Unfortunately, to the authors’ knowledge, there are no published studies of steady-state insulin pharmacology in patients with type 2 diabetes." (PMID 21410860, 2011). "The Goto-Kakizaki (GK) rat is a well-studied non-obese spontaneous type 2 diabetes (T2D) animal model characterized by impaired glucose-stimulated insulin secretion (GSIS) in the pancreatic beta cells." (PMID 21490936, 2011). "Western blot analysis of some proteins involved in insulin-induced glucose metabolism in the muscle tissue in the present study has revealed significantly decreased membrane Glut-4 and cytosolic IRS-1 expressions in high-fat diet-induced type 2 diabetes." (PMID 21785636, 2011). "Human studies have also shown that high protein diet, which provides increases in dietary leucine, can reduce glycemia in patients with type 2 diabetes without effect on body weight, but this is, at least in part, due to improved insulin secretion." (PMID 21731668, 2011). "Reduced myocardial FDG metabolism under fasting, glucose loading, and insulin clamping in patients with type 2 diabetes without CAD has been reported." (PMID 21841971, 2011). "In patients with long term type 2 diabetes and suboptimal stable insulin treatment, the addition of pioglitazone but not metformin reduced the level of inflammatory biomarkers such as MMP-9 and hs-CRP and increased insulin sensitivity and adiponectin." (PMID 21756323, 2011). "At first, the pancreatic beta-cells are able to compensate by increasing insulin secretion, but, as insulin resistance worsens, type 2 diabetes occurs when the pancreas fails to sustain this compensatory activity." (PMID 21298090, 2011). "This is the first study to show that controlling post-meal hyperglycaemia with a prandial + basal insulin regimen vs. a basal insulin regimen can attenuate the meal-induced increases in hsCRP, interleukin-6 and TNF-α in patients with Type 2 diabetes on metformin." (PMID 21517955, 2011). "Most people with type 2 diabetes do not use insulin, but rather oral medication and lifestyle changes such as diet and physical activity." (PMID 21979293, 2011).
type 2 diabetes (continued). "We have observed that vascular insulin sensitivity was deteriorated after treatment with metoprolol in patients with type 2 diabetes, whereas no change was found after treatment with carvedilol." (PMID 21999413, 2011). "There are no other studies comparing rapid-acting insulin analogues in patients with type 2 diabetes, or comparisons of the pharmacology of rapid-acting insulin analogues in type 2 relative to type 1 diabetes." (PMID 21410860, 2011). "Another oral insulin under development known as NN1952 has recently completed Phase 1 studies with an objective to study safety, tolerability, pharmacokinetics and pharmacodynamics in healthy subjects and subjects with type 1 and type 2 diabetes." (PMID 21059246, 2010). "Reduction in ghrelin after intravenous glucose bolus in subjects with type 2 diabetes suggests that early insulin response does not affect plasma ghrelin." (PMID 20700400, 2010). "In individuals with type 2 diabetes, the first-phase insulin response is severely diminished or absent, resulting in persistently elevated postprandial glucose throughout most of the day." (PMID 20843379, 2010). "With Type I diabetes, and in some patients with Type II diabetes, the lack of insulin can best be supplemented by providing new insulin-producing cells." (PMID 20195523, 2010). "In a recent publication, GIP-receptor agonists were found still to increase insulin levels in subjects with newly diagnosed type-2 diabetes, but postprandial glucose excursions were not improved, possibly due to a simultaneous glucagonotropic effect." (PMID 20204054, 2010). "There have been no trials against NPH insulin, which is more cost-effective in type 2 diabetes than the long-acting analogues." (PMID 21143938, 2010). "On the contrary, the initiation of insulin in individuals with type 2 diabetes, even if it is not titrated to reduce blood glucose levels, was found to reduce β-cell stress and improve the conversion rate of IP." (PMID 20415692, 2010). "Hyperinsulinemia is one of the characteristic features for type 2 diabetes; hence, the case population showed higher insulin values than the control population but it did not meet the statistical significance." (PMID 21031055, 2010). "Hyperinsulinemia is one of the characteristic features for type 2 diabetes; hence, the case population showed higher insulin values than the control population but it was not statistically significant." (PMID 21031055, 2010). "Clinical studies conducted by IMRA have shown Madeglucyl to be effective in helping to manage both Type I and Type II diabetes; in Type I diabetes, it reportedly reduces (but does not eliminate) daily insulin requirements." (PMID 21144080, 2010). "Proinsulin concentrations are increased relative to insulin in both IGT and type 2 diabetes." (PMID 21162746, 2010). "In contrast, mice lacking Irs2 develop type 2 diabetes, with Irs2-/- male mice displaying both insulin resistance and β-cell failure at an early age." (PMID 20604929, 2010). "The insulin users did not continue with the rest of the survey as they did not meet the inclusion criteria (i.e. Type 2 diabetes treated with lifestyle or oral medications)." (PMID 21092171, 2010). "Finally, in 353 subjects with type 2 diabetes, MET or placebo were added to ongoing insulin therapy and their effects on endothelial function and inflammatory markers were evaluated." (PMID 20804556, 2010). "MET therapy is weight neutral in patients with type 2 diabetes and may limit the weight gain experienced with SFU, TZD, or insulin therapy." (PMID 20804556, 2010). "Receptor MT1 is mainly expressed in alpha cells while MT2 is predominantly expressed in beta cells and upregulated in pancreatic islets of type 2 diabetic patients, suggesting that MT2 receptor may play a role in insulin secretion and type 2 diabetes." (PMID 20398260, 2010).